PPP1R12B (protein phosphatase 1 regulatory subunit 12B)
Description:
Regulates myosin phosphatase activity. Augments Ca(2+) sensitivity of the contractile apparatus.
Synonyms: MYPT2; M20; MGC87886; MGC131980; PP1bp55
Tractability: Antibody: the Human Protein Atlas places it where antibodies can reach. PROTAC: ubiquitination databases record sites on it; its protein half-life has been measured.
Gene: Protein-coding gene on chromosome 1 (202,348,666 to 202,592,706, forward strand). Ensembl gene ENSG00000077157.
Subcellular location: Cytoplasm, cytoskeleton; Cytoplasm, cytoskeleton, stress fiber
Subcellular location (Human Protein Atlas): Actin filaments; Plasma membrane
Pathways (Reactome):
Signal Transduction: RHO GTPases Activate ROCKs; RHO GTPases activate CIT; RHO GTPases activate PAKs; RHO GTPases activate PKNs
Cell Cycle: Regulation of PLK1 Activity at G2/M Transition
Gene Ontology:
Molecular function: protein binding; enzyme activator activity; enzyme inhibitor activity; myosin phosphatase regulator activity; phosphatase regulator activity; protein kinase binding
Biological process: neuron projection morphogenesis; regulation of muscle contraction; signal transduction
Cellular component: A band; cytoplasm; cytosol; nucleoplasm; Z disc; cytoskeleton; stress fiber
Genetic constraint (gnomAD): Loss-of-function variants: 69 observed, 115.88 expected, observed/expected ratio (o/e) 0.6, 90% interval 0.49 to 0.73. The synonymous counts are far from expectation, so gnomAD's model fits this gene poorly and the ratio says little. Missense variants: 1,002 observed, 1,169.2 expected, observed/expected ratio (o/e) 0.86, 90% interval 0.81 to 0.9. Synonymous variants: 344 observed, 430.08 expected, observed/expected ratio (o/e) 0.8, 90% interval 0.73 to 0.88.
Homologues: Orthologues: chimpanzee PPP1R12B (99% identical), macaque PPP1R12B (97% identical), dog PPP1R12B (91% identical), mouse Ppp1r12b (90% identical), rabbit PPP1R12B (90% identical), rat Ppp1r12b (88% identical), guinea pig PPP1R12B (87% identical), pig PPP1R12B (79% identical), Drosophila melanogaster Mbs (31% identical), Caenorhabditis elegans mel-11 (27% identical). Paralogues in human: PPP1R12A (50% identical), PPP1R12C (32% identical), PPP1R27 (6% identical).
Diseases named in the same sentence as PPP1R12B in open-access papers:
PPP1R12B is named in the same sentence as 26 diseases in open-access papers, as found by Europe PMC text mining. Sharing a sentence is not in itself a finding about the gene and the disease. The quoted sentences say what the papers report.
colorectal cancer (5 papers, 2017 to 2026). A primary or metastatic malignant neoplasm that affects the colon or rectum. "For example, PPP1R12B has been demonstrated to act as a tumor suppressor in colorectal cancer and esophageal carcinoma, while paradoxically serving as an oncogenic factor in Wilms’ tumor and breast cancer." (PMID 40612101, 2025). "Notably, PPP1R12B acted as a tumor suppressor in colorectal cancer and esophageal cancer, but as an oncogenic factor in Wilms’ tumor and breast cancer." (PMID 40612101, 2025).
atherosclerosis (3 papers, 2020 to 2025). A disease characterized by the build-up of fatty material and calcium deposition in the arterial wall resulting in partial or complete occlusion of the arterial lumen. "Although little is known about the association of PPP1R12B with atherosclerosis according to existing reports, the finding we revealed provided a valuable cue or direction for further and deeper investigation." (PMID 32096479, 2020). "miR-342–5p, associated with atherosclerosis, when overexpressed in ADSCs, binds to protein phosphatase 1 regulatory subunit 12B in human atherosclerotic plaque models, fostering apoptosis of damaged human umbilical vein endothelial cells and thereby safeguarding against atherosclerosis." (PMID 40242037, 2025). "The regulatory mechanism between miR-342-5p and its screened target (PPP1R12B), or the role of ADSCs-derived exosomes in the former both (miR-342-5p and PPP1R12B) in atherosclerosis is not further focused on and explored." (PMID 32096479, 2020). "In no small measure was therefore PPP1R12B a target of miR-342-5p in atherosclerosis." (PMID 32096479, 2020).
Autoimmunity (2 papers, 2013 to 2020). The occurrence of an immune reaction against the organism's own cells or tissues. "It is also noteworthy that both PRDM15 and PPP1R12B have been related to immune dysfunction and/or autoimmunity, mechanisms that are thought to play a key role in COPD pathogenesis." (PMID 32824824, 2020). "Hence, PRDM15 is overexpressed in B-cell dysregulation, a characteristic feature of COPD, whereas PPP1R12B and its “M20” transcript are higher in patients with celiac disease autoimmunity." (PMID 32824824, 2020). "For the PPP1R12B gene, Isoform c and d (transcript variants NM032103.2 and NM032104.2) also known as the small subunit (sm-M20) of myosin light chain phosphatase, show significant up-regulation in patients with CD autoimmunity compared to control patients." (PMID 23936387, 2013).
celiac disease (2 papers, 2015 to 2020). An autoimmune genetic disorder with an unknown pattern of inheritance that primarily affects the digestive tract. "Although its effect of interaction with PPP1R12B is currently unknown, it indicates a connection between changes in cytoskeleton rearrangements and the immune response predisposing to the chronic inflammation in celiac disease." (PMID 26123480, 2015). "Two of our eleven selected genes (GLS and PPP1R12B) map within celiac disease genome-wide significant loci." (PMID 26123480, 2015). "The differential expression of NTS and PPP1R12B indicate a potential role for smooth muscle contractility and cell proliferation in celiac disease, whereas other genes like GLS, NCALD and INSR suggests involvement of nutrient signaling and energy homeostasis in celiac disease pathogenesis." (PMID 26123480, 2015). "The differential expression of NTS and PPP1R12B indicate a potential role for smooth muscle contractility and cell proliferation, whereas other genes like GLS, NCALD and INSR suggests involvement of nutrient signaling and energy homeostasis in celiac disease pathogenesis." (PMID 26123480, 2015).
abdominal aortic aneurysm (1 paper, 2025). Enlargement and ballooning of the vessel that supplies arterial blood to the abdomen, pelvis and legs. "The PPP1R12B was identified as a key biomarker for abdominal aortic aneurysm prediction: its downregulation in this disease was linked to increased N6-methyladenosine levels." (PMID 41153660, 2025).
adenomyosis (1 paper, 2021). The growth of endometrial tissue inside the muscular wall of the uterine corpus. "In the present study, the low expression levels of PPP1R12C and PPP1R12B were partly related to the myometrium injury in adenomyosis, and anti-NGF therapy might be advantageous for repair of myometrial defect." (PMID 32676925, 2021).
bile duct tumor (1 paper, 2025). "As results, the following factors were included in further multivariate analysis: PPP1R12B expression, tumor size, lymph node metastasis, distant metastasis, TNM stage, bile duct tumor thrombus, and vascular invasion." (PMID 40612101, 2025).
bladder cancer (1 paper, 2019). "The shared mRNA was PPP1R12B, which was significantly downregulated in bladder cancer in our sequencing result and in the TCGA database." (PMID 30984788, 2019). "From our bioinformatics analysis, we speculate hsa_circ_0018069 is involved in pathways related to tumorigenesis and development of bladder cancer mainly through sponging miR-181b-5p to suppress expression of PPP1R12B." (PMID 30984788, 2019).
childhood asthma (1 paper, 2020). "Interestingly, Freĭdin and coworkers postulated PPP1R12B as a candidate gene for childhood asthma, but these data have not been replicated in other populations." (PMID 32824824, 2020).
endometrial polyp (1 paper, 2024). A benign nodular lesion protruding above the surface of the endometrium. "Relevant critical genes were downregulated in endometrial polyps, including ACTA2, KCNMB1, KCNMB2, PPP1R12B, MYL9, and ACTG2." (PMID 38473810, 2024).
hepatocellular carcinoma (1 paper, 2025). A malignant tumor that arises from hepatocytes. "While our previous study identified the inhibitory role of PPP1R12B in hepatocellular carcinoma (HCC), the precise molecular mechanisms underlying its anti-proliferative effects remain unclear." (PMID 40612101, 2025).
tumor (10 papers, 2016 to 2026). "In this study, we integrated clinical data with functional experiments to delineate the molecular basis of PPP1R12B-mediated tumor suppression in HCC proliferation." (PMID 40612101, 2025). "The results revealed significant downregulation of PPP1R12B mRNA in HCC tissues relative to adjacent non-tumor controls." (PMID 40612101, 2025). "Xenograft experiments and quantitative analysis revealed a significant reduction in mean tumor weight in PPP1R12B-overexpressing mice relative to control groups." (PMID 40612101, 2025). "Western blot and immunohistochemistry (IHC) experiments of 29 paired samples revealed significantly lower PPP1R12B protein expression in HCC tumor tissues compared to matched adjacent non-tumor tissues." (PMID 40612101, 2025). "Using PPP1R12B-overexpressing Huh7 cells and controls cells, we performed xenograft tumor experiments in nude mice, periodically measuring tumor volume to compare growth rates between groups." (PMID 40612101, 2025). "Collectively, our findings elucidated a novel tumor-suppressive role of PPP1R12B in HCC through modulation of the PAK2/β-catenin/Cyclin D1 axis." (PMID 40612101, 2025). "Meanwhile, each inoculation including Huh7 cells with PPP1R12B-overexpression developed into a slowly growing and small tumor than controls." (PMID 40612101, 2025). "The expression of the TGFBR2(p = 0.001), PPP1R12B(p = 0.010) were downregulated in tumor tissues, while the expressions of miR-17-5(p < 0.000) were upregulated in tumor tissues." (PMID 35241117, 2022). "Additionally, overexpression and silence of PPP1R12B experiments showed that PPP1R12B overexpression restricted cell proliferation and colony formation in vitro, and inhibited xenografted tumor growth in vivo, while its knockdown had opposite effects." (PMID 40612101, 2025). "These overexpression and knockdown results suggested PPP1R12B might function as tumor suppressor in HCC cell proliferation." (PMID 40612101, 2025). "Indeed, our findings suggest that down regulation of PPP1R12B impairs tumour cell migration through its influence on cellular force machinery and adhesion dynamics." (PMID 27531518, 2016). "In summary, our study delineates a previously unrecognized tumor-suppressive pathway in HCC proliferation, linking PPP1R12B to cell cycle control via PAK2/β-catenin/Cyclin D1 axis." (PMID 40612101, 2025).
cancer (6 papers, 2020 to 2025). A tumor composed of atypical neoplastic, often pleomorphic cells that invade other tissues. "We then focused on two target genes, PPP1R12A and PPP1R12B, for subsequent analysis, as both are members of the same gene family and enriched in the pathway of focal adhesion, proteoglycans in cancer and regulation of the actin cytoskeleton." (PMID 34180758, 2021). "The network revealed that CRC-related DERs such as hsa-miR-1-3p, hsa-miR-490-3p, hsa-miR-542-5p, hsa-miR-424-5p, and hsa-miR-133a-3p are associated with the regulation of several cancer-related pathways by targeting TIMP3, FOS, PPP1R12B, CCND2, and EGFR." (PMID 32153636, 2020). "In other cancer types, PPP1R12B exhibits contradictory functions." (PMID 40612101, 2025). "However, studies have shown MYPT to correlate significantly with drug resistance and poor prognosis in human carcinomas, thus postulating a plausible role of PPP1R12B in drug resistance and poor prognosis in OSCC or HNSCC." (PMID 32961854, 2020). "These DNAm sites were mapped to genes that play mechanistic roles in multiple cancers, such as cg06513015 on ERV3-1, cg09516963 on DYRK2, cg26919182 on PPP1R12B, and cg17612569 on GABPA and ATP5J." (PMID 36966332, 2023). "Two potential targets enriched in ‘proteoglycans in cancer’ pathway, PPP1R12A and PPP1R12B, were downregulated at both the mRNA and protein levels." (PMID 34180758, 2021). "Unfortunately, no previous study has reported a relationship between PPP1R12B and cancers, so a role for PPP1R12B in the development of tumors still needs to be identified." (PMID 34180758, 2021).
PPP1R12B also shares sentences with these, for which no sentence is quoted: breast carcinoma (1 paper); cardiac hypertrophy (1); esophageal carcinoma (1); heart failure (1); immune dysfunction (1); left ventricular hypertrophy (1); lymph node metastasis (1); Nephropathy (1); osteoporosis (1); osteosarcoma (1); polyp (1); type 2 diabetes (1); Wilms tumor (1).